CLDN2 (claudin 2)
Diseases named in the same sentence as CLDN2 in open-access papers (continued):
Sharing a sentence is not in itself a finding about the gene and the disease.
bacterial infection (5 papers, 2013 to 2025). "In the case of bacterial infection or toxins, an increase in claudin-2 levels is considered an adaptive process aimed at flushing out the toxin or bacteria." (PMID 38203449, 2023). "Bacterial infection dramatically decreased OCLN, CLDN-2, and ZO-1 gene expression in the ileum, but probiotic administration significantly boosted OCLN, ZO1, and CLDN -2 mRNA expression." (PMID 39203472, 2024). "However, the involvement of claudin-2 in bacterial infection in the intestine remains unknown." (PMID 23505542, 2013). "Likewise, bacterial infection significantly decreased OCLN, ZO1, and CLDN-2 gene expression in the jejunum, but probiotic supplementation boosted OCLN gene expression." (PMID 39203472, 2024).
intestinal diseases (4 papers, 2013 to 2024). "Decreased tight-junction protein expression as well as increased expression of leaky junction proteins, e.g., claudin 2, have been associated with epithelial leakiness and intestinal diseases." (PMID 32306098, 2020). "Changes to claudin-2 are associated with many intestinal diseases, including active IBD." (PMID 23505542, 2013).
inflammation (3 papers, 2019 to 2022). Aberrant reaction of the microcirculation characterized by movement of fluid and leukocytes from the blood into extravascular tissues. "At the same time, it was found that glutamate could increase the expression of ZO-1, occludin-1, claudin-2, claudin-3, and other tight junction protein, thereby improving the barrier damage caused by intestinal inflammation." (PMID 31772935, 2019).
gastrointestinal disease (2 papers, 2022 to 2024). A disease that occurs in the gastrointestinal system, excluding the hepatobiliary system. "Research on CLDN2 has primarily focused on gastrointestinal diseases, due to its role as a member of the tight junction protein family, prompting extensive investigation into its role about the intestinal barrier." (PMID 38425650, 2024).
immune disorders (2 papers, 2023). "If an insult/antigen is acute (DSS, pathogen), high claudin 2 levels are likely beneficial as this claudin supports wound repair; however, for chronic insults (immune dysfunction), high claudin 2 is likely detrimental as antigen exposure would increase." (PMID 37239907, 2023).
liver (2 papers, 2018 to 2019). "High claudin-2 in malignant cells at the IM was more commonly seen in colon than in rectum tumors." (PMID 29134439, 2018). "Claudin-2 and Afadin interact with one another predominantly in the membrane fraction, suggesting that l-Afadin might be important for growth in soft agar and formation of liver metastases." (PMID 30692208, 2019).
gynecological tumors (1 paper, 2020). "Mostly, an overexpression of claudin-2 in gynecological tumors has been observed." (PMID 32140805, 2020).
Kidney Disease (1 paper, 2019). "Reduced claudin-2 expression was also recorded in various kidney disease animal models, including cisplatin-induced nephrotoxicity, diabetic nephropathy and obstructive nephropathy-induced fibrosis." (PMID 31726679, 2019). "Although a direct role of claudin-2 in kidney disease has not been definitively established, several observations suggest a possible link." (PMID 31726679, 2019).
CLDN2 also shares sentences with these, for which no sentence is quoted: enteropathy (3 papers); necrotizing enterocolitis (3); squamous cell carcinoma (3); endometrial cancer (2); gastrointestinal disorders (2); hepatocellular carcinoma (2); Hypocalcemia (2); idiopathic hypercalciuria (2); ileitis (2); age-related hearing loss (1); bacteremia (1); bladder tumor (1); Canavan disease (1); cervical adenocarcinoma (1); collagenous colitis (1); congenital myasthenic syndrome (1); depression (1); endometrioid endometrial carcinoma (1); endotoxemia (1); fibrosis (1); gastric adenocarcinoma (1); gastroesophageal junction adenocarcinoma (1); genitourinary cancers (1); gout (1); head and neck squamous cell carcinoma (1); HIV enteropathy (1); HIV-1 infection (1); Hypercalcemia (1); Hypertension (1); hypertrophic cardiomyopathy (1).
A further 15 diseases each share a sentence with CLDN2 in 1 paper.